BRD4 (bromodomain containing 4)
Diseases named in the same sentence as BRD4 in open-access papers (continued):
Sharing a sentence is not in itself a finding about the gene and the disease.
breast cancer (continued). "In addition, as BRD4 has a protective role in lung and breast cancer, it can promote leukemia and lymphoma." (PMID 37509171, 2023). "Breast cancer studies have also revealed opposing functions of BRD4 isoforms." (PMID 37509171, 2023). "Combining BRD4 and Peli1 targeting is necessary for effective breast cancer treatment." (PMID 38179042, 2023). "For example, BRD4 regulates breast cancer dissemination through Jagged1/Notch1 signaling." (PMID 34605158, 2022). "For proof-of-concept, we demonstrate that tumour-specific BRD4 degradation with the bioorthogonal POLY-PROTAC nanoplatform combine with photodynamic therapy efficiently regress tumour xenografts in a mouse model of MDA-MB-231 breast cancer." (PMID 35882867, 2022). "Study shows BRD4 isoforms have opposing functions in breast cancer." (PMID 36171897, 2022). "Afterward, we investigated whether BRD4 degradation is a targeted strategy for Fgfr-S252W mammary tumors." (PMID 35547739, 2022). "In addition, it has recently been found that the combination of nimbolide, a covalent ligand of RNF114, with BRD4 inhibitor JQ1 to produce PROTAC 8, which targets BRD4, reduced BRD4 expression levels in 231MFP breast cancer cells." (PMID 36142231, 2022). "Similarly, the second bromodomain (BD2) of BRD4 interacts with diacetylated Twist via the same motif to promote tumorigenesis in basal-like breast cancer." (PMID 34540900, 2021). "Both RAC1 and BRD4 proteins predict poor survival in breast cancer patients." (PMID 34803511, 2021). "In basal-like breast cancer, a significant increase in bromodomain-containing protein 4 (BRD4), lysine-specific demethylase 5B (KDM5B), and enhancer of zeste homolog 2 (EZH2) activities was detected in tumor cell populations after treatment with MEK and PI3K/mTOR inhibitors." (PMID 33597817, 2021). "Thus, BRD4 activity has been found to be required for proliferation and ERα function in ER+ breast cancer cells, and promotes the migration and invasion of triple negative tumors through controlling Jagged1 expression." (PMID 33809005, 2021). "To analyze the effect of BET-PROTACs on HER2+ breast cancer, we first evaluated the efficacy of two well-known BRD4 degraders, MZ1 (based on the BETi JQ1) and ARV-825 (based on the BETi OTX015) in the HER2-overexpressing breast cancer cell lines BT474 and SKBR3." (PMID 33741018, 2021). "Moreover, we tested the expressions of NFKB1, RAC1and BRD4 in different molecular subtypes of breast cancer cells followed by NSC/JQ1 combined treatment." (PMID 34803511, 2021). "Next, we were interested in the effect of Rg3-CNT on BRD4 and PD-L1 in breast cancer cells." (PMID 34111025, 2021). "In this study, we elucidated a novel mechanism that breast cancer brain metastasis may be regulated by circBCBM1/miR-125a/BRD4 signaling axis." (PMID 34421353, 2021). "Brd4 is a member of the Bromodomain family of proteins, which play a key role in the epigenetic regulation of transcription and interacts with the oestrogen receptor in animal models of endometrial and breast cancer." (PMID 32927694, 2020). "For instance, BRD4 could induce cell migration and invasion in hepatocellular carcinoma and breast cancer." (PMID 31621555, 2020). "In contrast, BRD4 is downregulated in colon and breast cancers." (PMID 32099528, 2020). "Interestingly, a recent study reported that BRD4 modulates the spread of breast cancer by Notch1/Jagged1 signaling." (PMID 33135348, 2020).
breast cancer (continued). "Furthermore, there is evidence to suggest that BRD4-induced up-regulation of c-MYC played a critical role in inducing resistance to everolimus in ER+ breast cancer cells." (PMID 32218352, 2020). "The binding of BRD4 with the promoter region of stemness associated gene WNT5A is shown to enhance the tumor cell regeneration and invasiveness of TISCs in in basal-like breast cancer." (PMID 32218352, 2020). "Our data show that prolonged treatment of luminal breast cancer cells with AKT inhibitors induces FOXO3a dephosphorylation, nuclear translocation, and disrupts its association with SirT6, eventually leading to FOXO3a acetylation as well as BRD4 recognition." (PMID 30518851, 2018). "Thus, ZMYND8 expression is likely regulated by multiple mechanisms, including gene amplification, ERα, and possibly BRD4 pathways in breast cancer." (PMID 28055972, 2017). "Luminal/HER2+ cells were more sensitive to BRD4 knockdown than basal breast cancers." (PMID 27283767, 2016). "BRD4 has been shown to combine with Twist to induce epithelial-mesenchymal transition (EMT) in breast cancer in a previous study, which may indicate that BRD4 could promote NSCLC cell invasion." (PMID 26840017, 2016). "Inhibition of BRD4-promoter interactions has been shown to suppress the expression of important cell growth and survival genes, resulting in cell cycle arrest and extensive apoptosis in ER+ breast cancer, leukemia and lymphoma cells." (PMID 26378038, 2015). "We therefore assessed BRD4 expression in the investigated breast cancer cell lines." (PMID 26378038, 2015). "Moreover, BRD4 is required for the growth of ERα-positive tamoxifen-resistant breast cancer where it functions to promote ERα-dependent gene transcription." (PMID 25788266, 2015). "BRD4 was also reported to regulate metastasis in breast cancer." (PMID 25788266, 2015). "Genomic Regions Enrichment of Annotations Tool (GREAT) analyses on distal intergenic regions which exhibited overlapping peaks of H3K27ac, H4K12ac and BRD4 demonstrated an enrichment of estrogen and breast cancer luminal upregulated and basal downregulated-related pathways." (PMID 25788266, 2015). "Multiple ECM genes are regulated by BRD4 that may lead to changes in the overall structure of the surrounding environment or alter the cell-matrix interactions to promote breast cancer invasion and metastasis." (PMID 22570792, 2012). "The gene expression signature induced by the Brd4 short isoform, however, predicted poor outcome in these human breast cancer datasets, confirming that the shorter isoform might be a competitive inhibitor of the longer isoform." (PMID 22295248, 2012). "The review by J. Alsarraj and K. W. Hunter, “Bromodomain-containing protein 4: a dynamic regulator of breast cancer metastasis through modulation of the extracellular matrix”, is focused on the activity of bromodomain-containing protein 4 (BRD4) in breast cancer cells." (PMID 22570792, 2012). "Indeed, we found that ectopic expression of Brd4 in a highly metastatic mouse mammary tumor cell line reduces both primary tumor growth and metastatic capacity in our mouse model." (PMID 22295248, 2012). "While combining miR‐34b with JQ1, a BRD4 inhibitor, could present a therapeutic option for breast cancer patients, this approach warrants further investigation, particularly in the context of TNBC, where the oncogenic role of miR‐34b must be carefully considered." (PMID 41031256, 2025). "Furthermore, BRD4 expression in breast cancer tissues correlates with higher levels of infiltrating myeloid cells, and it appears that BRD4 inhibitors may alter the composition of the tumor microenvironment (TME)." (PMID 40762981, 2025). "In conclusion, our study displayed that SZU-101 (a TLR7 agonist synthesized by our group) and JQ-1 (a well-defined BRD4 inhibitor) could be administrated in combination to achieve better repressive effects on tumor growth and metastasis in both murine breast cancer and melanoma models." (PMID 38203835, 2024).
breast cancer (continued). "After analyzing the binding mode of compound 7 and BRD4 through molecular docking, we believed that proper structural modification of compound 7 could improve its binding ability with BRD4 to obtain potent BRD4 inhibitors, which was conducive to our next research on anti-breast cancer." (PMID 38099141, 2023). "Since we found that SEs are associated to NSMCE2 and MAL2 expression in breast tumors, we hypothesized that in breast cancer cells, expression of these genes should be reduced when disrupting the SE-enhancing function by blocking the binding of BRD4 to SEs with the inhibitors JQ1 or IBET151." (PMID 36224576, 2022). "The observed growth arrest is consistent with the degradation of BRD4 and the suppression of downstream c-Myc as well as with previous studies by our laboratory and others demonstrating c-Myc to be upregulated in ER+ breast cancer and involved in breast cancer proliferation." (PMID 36741704, 2022). "Therefore, we speculate that BRD4 may be involved in breast cancer brain metastasis by upregulating MMP9, resulting in BBB disruption, and thereby promoting the initiation and progression of brain metastasis." (PMID 34421353, 2021). "Furthermore, small-molecule bromodomain-containing protein-4 (BRD4) inhibitor displayed a potent antitumor effect on the zebrafish breast cancer model by targeting BRD4 without causing any cytotoxic effect." (PMID 32792514, 2020). "Hence, we examined the BRD4 expression and clinicopathological features of breast cancer." (PMID 30029633, 2018). "Finally, we confirmed that SRPK1 inhibition also alters BRD4 splicing in breast cancer cells, a finding that may be of therapeutic significance in metastasis prevention." (PMID 30568163, 2018). "In further support of this hypothesis, BRD4 was recently identified as a potential target in tamoxifen-resistant breast cancer, but has not yet been linked to mTOR inhibitors." (PMID 25537515, 2015). "Since BRD4 has both metastasis inhibiting and metastasis enhancing capacities due to the opposing effects of the two isoforms, the effect of these inhibitors on long term survival in breast cancer patients remains unclear." (PMID 24260471, 2013). "Di-acetylated TWIST can recruit and bind the bromodomain-containing protein 4 (BRD4), which is involved in EMT and cancer cell motility, to control WNT5A gene expression in basal-like breast cancer (BLBC)." (PMID 39942749, 2025). "(NCT06943521) for BRD4‐dependent solid tumors, covering broad tumor types including NSCLC, breast cancer, and prostate cancer." (PMID 41049269, 2025). "In breast cancer, BRD4 reorganises chromatin and facilitates recruitment of the LSD1–NuRD complex to SEs, which in turn with BRD4 occupies SEs, thereby repressing genes, and is functionally linked to drug resistance." (PMID 38542080, 2024). "The BRD4 protein (bromodomain-containing protein 4) regulates chromatin structure, and interactions between TWIST1 and BRD4 contribute to tumorigenesis in breast cancer." (PMID 38935814, 2024). "Early studies in breast cancer showed that BRD4 functions as a tumour suppressor and its overexpression in a MYC-driven murine mammary tumour cell line reduces breast cancer growth in vivo." (PMID 38191874, 2024). "Here, the 4T1 breast cancer model and the B16 melanoma model were applied because the antitumor effects of TLR7 agonists or BRD4 inhibitors were decided previously in these two types of cancers." (PMID 38203835, 2024). "For example, chromosomal rearrangements resulting in fusions of BRD3 or BRD4 with nuclear protein in testis (NUT) contribute to carcinogenesis in NUT midline carcinomas (NMCs), and BRD4 is an essential gene in luminal breast cancer." (PMID 38084912, 2024).
breast cancer (continued). "Knockdown of BRD4 and treatment with (+)-JQ1, a BRD4 inhibitor, both induce ferroptosis in breast cancer cell lines through ferritinophagy." (PMID 39595619, 2024). "Consistent with previous reports, ZBC260 reduced breast cancer cell levels of BRD2, BRD3, and BRD4 proteins in a concentration-dependent manner." (PMID 37968653, 2023). "BRD4 degrader reduced BRD4, PD-L1, RelB, and IL-6 levels and overexpression of PD-L1 of ARV-825 treated breast cancers increased reduced PD-L1, RelB, and IL-6 levels." (PMID 37924094, 2023). "APR exhibited robust Brd4 degradation (with a EC50 = 22 nM), potent cancer cell growth inhibition (IC50 = 56.9 nM in MCF breast cancer cells in vitro), and pronounced antitumor activity in MCF-7 tumor xenografts in vivo (TGI = 77.5%)." (PMID 37049806, 2023). "For example, BRD2 enhances epithelial-mesenchymal transition (EMT) in breast cancer cells, while BRD3 and BRD4 repress EMT." (PMID 37296612, 2023). "BRD4 inhibitor induces an immunostimulatory TME, at least in part, by inhibiting immunosuppressive cells in a breast cancer model." (PMID 37685868, 2023). "The bromodomain protein BRD4 has two major isoforms, BRD4-L and BRD4-S, with opposing biological functions in MDA-MB-231 breast cancer cells." (PMID 37665675, 2023). "This twist–BRD4 interaction is essential for expressing EMT-related genes and promotes tumorigenicity in breast cancer." (PMID 38072045, 2023). "Another research group found that methylated BAF155 shares genome binding sites with BRD4 and H3K27ac, and methylated BAF155 increased tumor metastasis by attracting BRD4 and activating SE-dependent oncogenes in breast cancer." (PMID 37501079, 2023). "ABBV-744 did not significantly alter the levels of BRD2 or BRD3; however, a significant downregulation in BRD4 levels was evident at both 75 nM and 100 nM, indicating the potential selectivity of ABBV-744 towards BRD4 in ER+ breast cancer cells." (PMID 37627092, 2023). "BRD4/LSD1/NuRD complex then represses the activation of drug-resistant genes such as WNT4, LRP5, BRAF, GNA13, and PDPK1 in breast cancer cells." (PMID 35740532, 2022). "MDM2 ligase, coupled with inhibitors of the targets BCL2L1, BRD4, CDK9, PLK1 and MCL1 in stomach cancer, and MDM2 with PIK3C3 inhibitors in breast cancer seemed to be the best therapeutic construction." (PMID 35249548, 2022). "The histidine cluster in the AD of YY1 compartmentalizes BRD4, MED1, and enhancer elements in phase-separated condensates to activate FOXM1 expression in breast cancer." (PMID 35740532, 2022). "MDM2 ligase coupled with inhibitors of the targets BCL2, BRD4, CDK9, PLK1 and MCL1 in stomach tumor, and MDM2 with PIK3C3 inhibitors in breast cancer, seems to be the best therapeutic strategy." (PMID 35249548, 2022). "While this has not been observed for FTL yet, it has been reported, that co-targeting of BRD4 and RAC1 disrupts the MYC/G9a axis and enhances the expression of FTH1 in breast cancer cells." (PMID 36231049, 2022). "For example, BRD4 and AKT are important for the proliferation of breast cancer cells, and their isomers are antagonized to each other." (PMID 35456460, 2022). "To examine its effect on the binding of BRD4 to TCOF1 super-enhancer and TCOF1 expression, we performed ChIP-qPCR and immunoblotting in JQ1- or dimethyl sulfoxide-treated breast cancer cells." (PMID 34718356, 2022). "While BRD2, BRD3, and BRD4 have partially redundant roles at ERα enhancers and gene transcription, a more unique role of BRD3 in ERα+ breast cancer is revealed." (PMID 34540900, 2021). "For instance, when overexpressed, BRD4 isoforms tend to have opposing functions in breast cancer, BRD4-S exhibits oncogenic properties, while BRD4-L has a tumor suppressor role." (PMID 34758842, 2021).
breast cancer (continued). "Opposing functions of BRD4 isoforms have also been studied in breast cancer, showing the oncogenic EN1–BRD4S axis and tumor-suppressive BRD4L in breast cancer, which demonstrates the context-dependent functions of long and short isoforms." (PMID 34540900, 2021). "We observed a reduction in RAC1 and BRD4 expressions in combination treated cells in comparison to control cell lines treated with DMSO in MCF-7, MDA-MB-231, SKBR3 and JIMT-1 breast cancer cells." (PMID 34803511, 2021). "Luminal breast cancer that received AKT inhibitor therapy can acetylate FOXO3a, which recognizes BRD4 and then recruits it to the CDK6 gene promoter and induces its transcription." (PMID 34834420, 2021). "Taken together, these results suggest that different molecular subtypes of breast cancer express high levels of RAC1 and BRD4 and amplification of both BRD4 and RAC1 signaling correlated with decreased survival of breast cancer patients." (PMID 34803511, 2021). "We also detected a correlation of RAC1 and BRD4 expressions with leukocyte infiltration and somatic copy number alteration (SCNA) in breast cancer samples." (PMID 34803511, 2021). "Based on high expression of both RAC1 and BRD4 in human breast cancer samples, we investigated the effect of high and low expression levels of RAC1 and BRD4 on survival of breast cancer patients." (PMID 34803511, 2021). "In breast cancer, ZMYND8 was found to interact with HIF-1α and HIF-2α, and it can also recruit of BRD4 and release paused RNA polymerase II to enhance the HIF-induced oncogenicity." (PMID 34834420, 2021). "Bromodomain-containing 4 (BRD4) knockdown and (+)-JQ1, an inhibitor of BRD4, induce ferroptosis via ferritinophagy in breast cancer cell lines." (PMID 33294126, 2020). "BRD2, a member of the bromodomain and extra-terminal (BET) family including mammalian BRD3, BRD4 and BRDT, is remarkably over-expressed in breast cancer, gastric cancer (GC), malignant pleural mesothelioma (MPM) and castration-resistant prostate cancer (CRPC)." (PMID 32927435, 2020). "While the BRD4/c-Myc and the integrin/FAK axes are promising targets for breast cancer, their functional interactions remain elusive." (PMID 33006750, 2020). "Based on our results, we conclude that the BRD4/c-Myc- and integrin/FAK-dependent pathways act in concert to promote breast cancer cell survival and poor clinical outcomes." (PMID 33006750, 2020). "In this study, response to flavopiridol and dinaciclib, breast cancer cells MCF7 through the activation of CDK inhibitor pathways and the chromatin reader BRD4 alter the histone marks H3K27me3K36me3." (PMID 32412527, 2020). "In particular, the authors demonstrated that the switch toward the long isoform of BRD4 induced by SRPK1 inhibition affects BRD4 recruitment to the chromatin in AML cells and is detected in breast cancer cells treated with SPHINX31." (PMID 31134126, 2019). "To further investigate the role of JQ1 in AR expressing breast cancer cells, we assessed protein-protein interactions among ATAD2, AR, as well as JQ1 targets including BRD2, and BRD4." (PMID 31527644, 2019). "Our study reports the involvement of BRD4/FOXO3a/CDK6 axis in AKTi resistance and provides potential therapeutic strategies for treating resistant breast cancer." (PMID 30518851, 2018). "BRD4 is a major target of BET inhibitors, such as JQ-1, which also suppress breast cancer growth inhibition in vitro and in vivo." (PMID 28055972, 2017). "More interestingly, recent studies have also showed that BRD4 activation may also predict the overall survival of patients with several tumors, such as melanoma, hepatocellular carcinoma, multiple myeloma, Burkitt's lymphoma, acute myeloid leukemia and breast cancer." (PMID 26840017, 2016). "In basal-like breast cancer, the TWIST protein, a well known EMT inducer, is specifically diacetylated by KAT5 to interact with BRD4 and activate WNT5A." (PMID 27581651, 2016).